ZEB2 (zinc finger E-box binding homeobox 2)
Diseases named in the same sentence as ZEB2 in open-access papers (continued):
Sharing a sentence is not in itself a finding about the gene and the disease.
adenoma (2 papers, 2018 to 2019). A neoplasm arising from the epithelium. "The majority of target genes (CDKN1B, PTPN13, RND3, SOX2 and ZEB2) were down-regulated in adenoma compared to normal mucosa." (PMID 31623346, 2019). "All investigated and expressed target genes, CDKN1B, PTPN13, RND3, SOX2 and ZEB2, were down-regulated in adenoma compared to normal mucosa of CRC N0, except ONECUT2 and TGFB2, which were up-regulated." (PMID 31623346, 2019). "Similarly, both of our cases that showed expression of SOX2 (also showing expression of PTPN13 and ZEB2) were adenomas with high-grade dysplasia." (PMID 31623346, 2019). "Moreover, PTPN13, SOX2 and ZEB2 showed detectable expression only in two out of 10 adenoma cases, whereas ONECUT2 and TGFB2 were up-regulated." (PMID 31623346, 2019). "In adenomas, differential expression in comparison with CRC N0 was also observed for ZEB2 (p = 0.034) and SOX2 (p = 0.046), and in comparison with CRC N+, ONECUT2 (p = 0.006) and RND3 (p < 0.001)." (PMID 31623346, 2019). "In contrast to adenoma, investigated target genes CDKN1B, PTPN13, RND3, SOX2 and ZEB2 were up-regulated in CRC N0, except ONECUT2 and TGFB2, which were down-regulated." (PMID 31623346, 2019). "Nuclear Yap1 was not evident in AAH, adenomas, or surrounding normal lung, but nuclear translocation occurred specifically in hypoxic clusters where a Zeb2-to-Zeb1 switch occurs in a Tgf-β1-rich environment." (PMID 29930325, 2018). "Moreover, PTPN13, SOX2 and ZEB2 were expressed only in two out of 10 samples of adenoma, so a calculation of statistical significance would not be appropriate." (PMID 31623346, 2019). "As opposed to Zeb1, we found immunostaining for Zeb2 in AAH, adenomas, and normal lung, and it was downregulated with Zeb1 induction in hypoxic cell clusters forming in the interior of adenomas." (PMID 29930325, 2018). "In turn, CD44 was not induced, Zeb2 was not repressed, and cells displaying an E-cadherin−, Pten− pattern of EMT were diminished in adenomas." (PMID 29930325, 2018).
Alzheimer disease (2 papers, 2024 to 2025). A progressive, neurodegenerative disease characterized by loss of function and death of nerve cells in several areas of the brain leading to loss of cognitive function such as memory and language. "ZEB2 has not previously been implicated in TREM2 regulation or in neurodegenerative diseases such as Alzheimer’s disease." (PMID 41300781, 2025).
benign prostatic hyperplasia (2 papers, 2013 to 2014). A non-cancerous nodular enlargement of the prostate gland. "The previous studies showed that TGF-β1 induces the expression of ZEB1, ZEB2, and SLUG, but not SNAI in benign prostatic hyperplasia epithelial cell line BPH-1 Cells." (PMID 24402783, 2014).
cleft palate (2 papers, 2016 to 2022). Cleft palate is a fissure type embryopathy that affects the soft and hard palate to varying degrees. "Among these genes, ablation or mutation of Alx3, Lhx8, Pax3, Pitx1, Shox2, and Zeb2 induces cleft palates in humans and/or mice." (PMID 27329940, 2016).
DiGeorge syndrome (2 papers, 2022 to 2026). "Genome‐wide, methylation changes in DBAS overlapped significantly with those of Mowat‐Wilson syndrome (ZEB2) and Velocardiofacial syndrome (VCFS; TBX1, DGCR8), suggesting shared downstream developmental pathways affected by ribosomal stress." (PMID 41247002, 2026).
Down syndrome (2 papers, 2017 to 2024). "This does not come as a total surprise, as several known HSCR genes (e.g., KBP, SOX10, NRG1, IKBKAP, ZEB2, PHOX2B) are involved in both CNS and ENS pathologies and the fact that HSCR is strongly associated with Down syndrome." (PMID 28274275, 2017).
dysplasia (2 papers, 2023). A usually neoplastic transformation of the cell, associated with altered architectural tissue patterns. "The target genes of many miRNAs can express transcription factors and are associated with cardiac dysplasia and apoptosis, such as Nkx2.5, Zeb2, Mef2c, and Ets1." (PMID 38053046, 2023).
gastric tumor (2 papers, 2015 to 2024). "In gastric tumor samples the expression levels of ZEB2 were inversely correlated with the expression of miR-141." (PMID 25975736, 2015). "The results suggest that the mRNA expression levels of ZEB2 may be inversely correlated with the expression levels of miR-141 in gastric tumor samples." (PMID 25975736, 2015). "The mRNA expression levels of miR-141 and ZEB2 were detected in nine gastric tumor and non-tumor tissues by qPCR." (PMID 25975736, 2015).
kidney (2 papers, 2021 to 2023). "RECK and ZEB2 are involved in cancer metastasis and are also associated with urogenital cancer networks." (PMID 33987019, 2021).
laryngeal carcinoma (2 papers, 2022). Carcinoma that arises from the laryngeal epithelium. "In laryngeal carcinoma clinical samples studied with immunohistochemistry, advanced staging and decreased differentiation correlate with E-cadherin downregulation, β-catenin nuclear translocation, and expression of the transcription factors Snail, Slug, and ZEB2." (PMID 36140250, 2022). "FoxO1 serves a necessary function in HDAC inhibitor‐based suppression of larynx carcinoma invasion and metastasis by blocking MMP7 or by binding the ZEB2 promoter and reversing ZEB2‐induced EMT." (PMID 33772986, 2022).
malignant glioma (2 papers, 2014 to 2016). A grade III or grade IV glioma arising from the central nervous system. "The current research has shown EMT-like changes in malignant gliomas, including a role for SNAIL1/SNAIL2, TWIST1/ TWIST2, ZEB1/ZEB2 and miRNAs as inducers for a cell-invasive phenotype in GBMs." (PMID 26761212, 2016). "EMT-like changes in malignant gliomas are attributed to TWIST1, ZEB1/ZEB2 and SNAIl1/SNAIl2 as inducers for cell-invasiveness in GBMs." (PMID 24475040, 2014).
mesenchymal tumor (2 papers, 2017 to 2023). "As a mesenchymal tumor, it is not clear whether EMT plays a role in ES metastasis at all, but many genes implicated in EMT, including TWIST1, ZEB2, and SNAIL1, have also been implicated in ES metastasis." (PMID 29108227, 2017).
myeloproliferative diseases (2 papers, 2023 to 2025). "It was presented in a hematologic study that ZEB2 knockout in the bone marrow could lead to phenotypes resembling myeloproliferative disorders, which may be mediated by its downstream JAK-STAT and ERK pathways, according to KEGG analysis." (PMID 40510028, 2025). "Interestingly, CXCR4 is the effector of ZEB2 in some hematopoietic cells, and genetic ablation of ZEB2 in hematopoietic lineage resulted in an increase in HSC and progenitors in the bone marrow and other specific features resembling myeloproliferative diseases in humans." (PMID 37259089, 2023).
oesophageal cancer (2 papers, 2022 to 2023). "PBX1 acted as pioneer transcription factor to mediate the binding of FoxC1 to ZEB2 promoter in oesophageal cancer cells." (PMID 35068042, 2022).
pancreatic adenocarcinoma (2 papers, 2019 to 2022). "Normalized mRNA expression data from TCGA studies of breast, prostate, lung, colorectal and pancreatic adenocarcinomas was downloaded for ZEB1, ZEB2, SNAI1, SNAI2, TWIST1, FOXQ1 and FOXC218,19." (PMID 31780722, 2019).
Peritoneal Fibrosis (2 papers, 2024). Disorder characterized by a wide range of structural changes in PERITONEUM, resulting from fibrogenic or inflammatory processes. "In this context, the link between miR-200a and its target genes (Zeb1 and Zeb2) in rats with peritoneal fibrosis related to peritoneal dialysis was investigated." (PMID 39968362, 2024).
psoriasis (2 papers, 2022 to 2024). An autoimmune condition characterized by red, well-delineated plaques with silvery scales that are usually on the extensor surfaces and scalp. "In the dynamic evolution process of EMT in psoriasis, as the KC marker Krt5 increased, the EMT markers Vim and Zeb2, and the IL-17 signalling pathway marker Il17ra clearly decrease." (PMID 38472183, 2024). "Furthermore, as the KC marker Krt5 increased, the EMT markers Vim and Zeb2, and the IL-17 signalling pathway marker Il17ra clearly decreased, which hinted at the existence of EMT in psoriasis and its intimate connection with the IL-17 signalling pathway." (PMID 38472183, 2024). "As with TEX41 (FC = 0.41, p = 1.4 × 10−5), ZEB2 (FC = 0.42, p = 2.8 × 10−12) is significantly downregulated in psoriasis, however there was no mQTL or other evidence for this gene." (PMID 36323703, 2022).
pulmonary emphysema (2 papers, 2022 to 2023). A subcategory of chronic obstructive pulmonary disease (COPD). "Meanwhile, there is evidence to suggest that miR-200b can further alleviate cellular senescence, as well as inflammatory responses in pulmonary emphysema by targeting ZEB2." (PMID 37759281, 2023).
rhabdomyosarcoma (2 papers, 2021 to 2023). A rare aggressive malignant mesenchymal neoplasm arising from skeletal muscle. "The presence of rare neoplasms such as rhabdomyosarcoma raises suspicion of a connection between ZEB2 impairment and this type of cancer." (PMID 33982229, 2021).
skin cancer (2 papers, 2018 to 2019). "Almost all skin cancer cell lines had high expression levels of ZEB2 and low levels of RAB25." (PMID 30445998, 2018).
acute kidney injury (1 paper, 2021). Sudden and sustained deterioration of the kidney function characterized by decreased glomerular filtration rate, increased serum creatinine or oliguria. "However, ZEB2 inhibited inflammatory cytokine secretion in acute kidney injury and was reported to be related to the NF-κB signaling pathway." (PMID 34421621, 2021).
acute respiratory distress syndrome (1 paper, 2022). Progressive and life-threatening pulmonary distress in the absence of an underlying pulmonary condition, usually following major trauma or surgery. "However, during the early stages of acute respiratory distress syndrome (ARDS) induced in a mouse model by lipopolysaccharides (LPS), it was also shown that miR200b/c was downregulated, which was associated with an increment of their protein targets ZEB1 and ZEB2." (PMID 35743055, 2022).
agenesis of the corpus callosum (1 paper, 2007). "Since agenesis of the corpus callosum is the only MWS feature that can be detected prenatally, molecular screening of the ZEB2 gene in prenatal isolated agenesis of the corpus callosum, has been carried out." (PMID 17958891, 2007).
alopecia (1 paper, 2017). Hair loss usually from the scalp. "The reduction of the dermal thickness and the occurrence of alopecia somewhat depended on the sites of Zeb2-cKO mice; that is, it was more pronounced on the limbs, scalp and interlimb flanks, but less on the back." (PMID 28422173, 2017). "However, Zeb2-cKO mice display hair loss (alopecia), which MOWS and EDS patients do not develop." (PMID 28422173, 2017).
aneurysm (1 paper, 2019). Bulging or ballooning in an area of an artery secondary to arterial wall weakening. "Higher ZEB1/ZEB2 expression, as well as a lower expression of the miR‐200 family, is compatible with an ongoing EndMT/EMT process in BAV that is aneurysm independent, and the transition to aneurysm state is most probably due to the further exasperation of a pre‐existing EndMT/EMT." (PMID 30280445, 2019).
aortic aneurysm (1 paper, 2024). A ruptured aneurysm located in the wall of the proximal portion of the descending aorta proceeding from the arch of the aorta. "Recent studies have shown that ZEB2 reduces the S-sulfhydration of protein disulfide isomerase by inhibiting the cystathionine γ-lyase/hydrogen sulfide system, thereby inducing the initiation of aortic aneurysms and dissections." (PMID 38566808, 2024).
brain injury (1 paper, 2025). Acute and chronic (see also brain INJURIES, CHRONIC) injuries to the brain, including the cerebral hemispheres, CEREBELLUM, and brain STEM. "In the realm of brain injury, miR-200c has been found to interact with the Zinc Finger E-Box Binding Homeobox 2 (ZEB2), playing a crucial role in modulating the progression and recovery of brain injury." (PMID 39129166, 2025).
Burkitt lymphoma (1 paper, 2021). A rare form of malignant mature B-cell non-Hodgkin lymphoma. "Contrary to the mRNA, the expression of ZEB1 and ZEB2 protein was upregulated in Burkitt lymphoma cells upon exposure to HIV-1, supporting the notion that the enhanced migration of BL cells via downregulation of hsa-miR-200c-3p leads to an alleviation of active repression of the ZEB proteins." (PMID 34573283, 2021).
cardiac hypertrophy (1 paper, 2024). "Blocking the function of miR-208a with anti-miR-208a increased ZEB2 expression in the heart and effectively protected from the development of pathological cardiac hypertrophy." (PMID 39308239, 2024).
cardiovascular malformations (1 paper, 2020). "ZEB2 has many functions in addition to its role during EndMT, its loss causes severe neurodevelopmental defects and cardiovascular malformations, while its specific effect during EndMT still needs to be elucidated." (PMID 32226439, 2020).
colorectal adenocarcinoma (1 paper, 2018). The most common type of colorectal carcinoma. "To determine whether ZEB2 expression correlates with Sp1 expression in human cancers, we analyzed TCGA-generated colorectal adenocarcinoma data (two cancer studies; TCGA, Nature 2012, and TCGA, Provisional)." (PMID 29416649, 2018). "Analysis of The Cancer Genome Atlas (TCGA)-generated colorectal adenocarcinoma data (two cancer studies; TCGA, Nature 2012, and TCGA, Provisional) showed that expression of ZEB1 is lower than or comparable to that of ZEB2." (PMID 29416649, 2018).
Congenital Central Hypoventilation Syndrome (1 paper, 2021). "Deletions of 2q and 4p contributed to the discovery of genes responsible for Mowatt-Wilson syndrome (ZEB2, formerly ZFHX1B) and the gene responsible for Congenital Central Hypoventilation Syndrome (PHOX2B)." (PMID 34358225, 2021).
ectodermal dysplasia (1 paper, 2017). "In cattle, anhidrotic ectodermal dysplasia is induced by a deletion in the ED1 (anhidrotic ectodermal dysplasia) gene, and polled and multisystemic syndrome is caused by a deletion that knocks out the ZEB2 (zinc finger E-box binding homeobox 2) gene." (PMID 29065859, 2017).
endometrioid carcinoma (1 paper, 2025). "FAM64A correlates with neither ZEB1, ZEB2 nor Snail1 in high-grade serous OC and endometrioid carcinoma." (PMID 40424038, 2025).
Fibroadenoma (1 paper, 2024). A benign tumor of the breast characterized by the presence of stromal and epithelial elements. "In contrast, fibroadenomas had elevated expression of Il6st, Lifr, Tgfβr2, and transcription factor Zeb2." (PMID 38334641, 2024).
gallbladder carcinoma (1 paper, 2020). "Overexpression of ZEB1 and Zeb2 in epithelial cells have been demonstrated to induce the EMT, and ZEB1 is expressed at high levels in invading lung, uterine, colorectal, endometrial, prostate, and gallbladder carcinomas." (PMID 32730336, 2020).
hydronephrosis (1 paper, 2026). Collection of urine in the renal pelvis that results in dilatation of the renal pelvis and calyces. "Deleting Zeb2 in these cells caused hydroureter and hydronephrosis, indicating obstructive uropathy." (PMID 41576029, 2026).
Hyperglycemia (1 paper, 2026). An increased concentration of glucose in the blood. "Here, we found that persistent hyperglycemia increases ZEB2 expression in wound macrophages via histone acetylation, contributing to chronic inflammation and delayed wound healing." (PMID 41609782, 2026). "Conversely, silencing Zeb2 at the wound site reduced hyperglycemia-induced macrophage inflammation." (PMID 41609782, 2026).
Immunodeficiency (1 paper, 2021). Failure of the immune system to protect the body adequately from infection, due to the absence or insufficiency of some component process or substance. "Whether ZEB2 exhibits similar expression patterns in human CD8 T cells is unknown, and MWS patients have not been comprehensively studied to identify changes in CD8 lymphocytes and NK cells, or manifestations of immunodeficiency." (PMID 34070208, 2021).
infertile (1 paper, 2022). "Plasma ZEB2 levels were significantly higher among patients with infertility compared to fertile women (16.07 ± 12.70 ng/L vs. 12.07 ± 11.92 ng/L; p < 0.04)." (PMID 36289723, 2022). "This stands in line with the results of our study, as patients with infertility and primary infertility presented significantly higher plasma ZEB2 levels, which downregulates E-cadherin." (PMID 36289723, 2022). "There were significant differences observed in ZEB2 levels between infertile and fertile patients (16.07 ± 12.70 ng/L vs. 12.07 ± 11.92 ng/L; p < 0.04)." (PMID 36289723, 2022). "The possible differences in ZEB2 plasma levels between patients with and without infertility indicate the possibility of EMT dysregulation in the pathogenesis of adverse fertility outcome, but further studies on a wider group of patients are required." (PMID 36289723, 2022). "The differences in ZEB2 plasma levels between patients with and without infertility indicate the possibility of EMT dysregulation in the pathogenesis of adverse fertility outcomes." (PMID 36289723, 2022).
influenza (1 paper, 2019). An acute viral infection of the respiratory tract, occurring in isolated cases, in epidemics, or in pandemics; it is caused by serologically different strains of viruses (influenzaviruses) designated A, B, and C, has a 3-day incubation period, and usually lasts for 3 to 10 days. "Published transcriptional profiles of NK cells, ILC1, and influenza-specific Id2-deficient mouse CD8+ T cells showed a striking concordance of Id2-dependent expression with our innateness gradient genes, highlighted by TBX21, ZEB2, IL18RAP, CCR7, TCF7, cytotoxicity, and KLR genes." (PMID 30737409, 2019).
intervertebral disc degeneration (1 paper, 2025). "In order to validate the potential transcription factor regulatory network, we conducted an analysis of the expression levels of IL-1β, ZEB2, TNFAIP6, and COL6A2 in intervertebral disc degeneration (IVDD) patients." (PMID 39704340, 2025). "Next, an investigation was conducted to determine if ZEB2 acts as a potential key transcription factor in regulating TNFAIP6 and COL6A2 in intervertebral disc degeneration." (PMID 39704340, 2025).
intestinal cancer (1 paper, 2022). "We then established ZEB2 over expression intestinal cancer stable transitional cell lines." (PMID 35884488, 2022). "We successfully established ZEB2 and TWIST1 knockdown intestinal cancer stable transitional cell lines by sgRNA and shRNA." (PMID 35884488, 2022).
Kawasaki disease (1 paper, 2022). A rare inflammatory disease characterized by an acute febrile, systemic, self-limiting, medium-vessel vasculitis primarily affecting children. "For example, beta-catenin contributed to the pathogenesis of Kawasaki disease, and a highly ranked gene of our EPIMISC signature was ZEB2." (PMID 35770252, 2022).
kidney damage (1 paper, 2023). "After this procedure, the rats were accompanied for 12 and 24 weeks after T1D induction and the renal function, structure, cell transdifferentiating markers and zinc finger e-box binding homeobox 1/2 (ZEB1/ZEB2) contribution to kidney damage were evaluated during the DKD progression." (PMID 37391399, 2023).